BCL2 (BCL2 apoptosis regulator)
Diseases named in the same sentence as BCL2 in open-access papers (continued):
Sharing a sentence is not in itself a finding about the gene and the disease.
tumor (continued). "Multivariable Cox proportional hazards model of stromal cell FOXC1 and tumor cell pERK1‐2 expression, NCCN‐IPI risk group, cell of origin, and MYC/BCL2 double expression in DLBCL patients (n = 92)." (PMID 39404228, 2024). "The activation of JNK dissociates the Bcl-2-Beclin-1 complex, which frees Beclin-1 from inhibition and activates autophagy to sustain the nutrient-deprived tumor cells." (PMID 38279220, 2024). "First, the impact and mechanism of BCL-2 inhibitors on the number and function of tumor-infiltrating immune cells (such as various B and T cells, dendritic cells, and natural killer cells) are unclear." (PMID 39060763, 2024). "Expression of Kiel 67 (Ki-67) proliferation marker and B-cell lymphoma 2 (BCL-2) anti-apoptotic protein was measured using immunohistochemistry (IHC) to estimate tumor growth and apoptosis." (PMID 39463509, 2024). "Studies have shown that anti-apoptotic proteins of BCL2 family, including Bcl-xL and BCL2, play an important role in the acquisition of radiation resistance in certain tumor types." (PMID 38383492, 2024). "In summary, understanding the impact of BCL2 TMD mutations at the molecular and functional level remains critical to unraveling the underlying mechanisms driving tumor behavior and developing precision treatments for affected patients." (PMID 38670940, 2024). "We previously showed that in luminal breast cancer, IL-6 secretion by CAFs mitigates the tumor BCL-2 dependency by inducing expression of cancer cell pro-survival protein MCL-113." (PMID 38898061, 2024). "Tumor cells displaying an up-regulated COX-2/Bcl-2 axis demonstrate heightened resistance to apoptosis and diminished effectiveness of chemotherapy medications." (PMID 38919710, 2024). "Phosphorylation of PI3K and AKT facilitates Bcl-2 release while dampening Bax activity, leading to the suppression of apoptosis in tumor cells." (PMID 38372808, 2024). "Further reduction in tumor growth was observed when the drug was administered with Venetoclax, a Bcl-2 inhibitor." (PMID 38571491, 2024). "The level of Bax in tumor cells increased with the 5-FU or Pro plus 5-FU treatment, while the Bcl-2 expression in tumor cells was the highest in the T+5-FU+Pro group." (PMID 39062024, 2024). "The tumor cells’ viability declined, improved apoptosis, decreased expression of Bcl-2, and increased Bax and Bcl/Bax ratio LNCaP and PC-3 cells." (PMID 38291541, 2024). "Previously, we showed that bcl2 siRNA molecules complexed with cationic lipid nanoparticles were able to effectively reduce tumor growth in a mouse model." (PMID 38892434, 2024). "We found a significant increase in the tumor-initiating cell population and increased expression of the pro-survival family member Bcl-2, which is widely known for its oncogenic behavior." (PMID 38928449, 2024). "When shCIP2A-transfected A549 cells were inoculated into nude mice, downregulation of Bcl2 and Bcl2 p-T69 in tumor tissues were detected." (PMID 38321019, 2024). "The miRNA-29c derived from exosomes induces apoptosis in tumor cells by downregulating BCL-2 and MCL-1 at both the mRNA and protein levels." (PMID 38298209, 2024). "The upregulation of anti-apoptotic BCL2 proteins represents an unfavorable prognostic factor in many tumor types due to their ability to shift the equilibrium toward cancer cell survival." (PMID 38670940, 2024). "ABT-737, the first BH3-mimetic to be developed, induced tumor regression through inhibition of BCL-2, BCL-xL and BCL-w." (PMID 39497108, 2024). "Usually, there is a down-regulation of Stat-3, Survivin and Bcl2 proteins and an up-regulation of Caspase-3 proteins by the AgNPs in the tumour cells." (PMID 37668757, 2024).
tumor (continued). "In our study, almost all neoplasms were positive for BCL2, CD99, CD56, FLI1, TLE1, MUC4, and PDGFR alpha." (PMID 39062853, 2024). "Overexpression of miR-9-5p significantly inhibited the proliferation of HCT116 and SW1116 cell lines by targeting the PAK4 kinase and acted as a tumor suppressor by downregulation of BCL-2 and upregulation of BAD." (PMID 39001526, 2024). "Our method applies a technique called attention-based multiple instance learning to regress the proportion of c-MYC-positive and BCL2-positive tumor cells from pathologist-scored tissue microarray cores." (PMID 38243330, 2024). "Overexpression of BCL-2 interferes with normal apoptotic signaling, increasing cell survival following IL-2 withdrawal and preserving T-cell capability to target tumor cells." (PMID 38891056, 2024). "Bcl-2 is also closely related to NEN differentiation, as Bcl-2 expression is closely linked to chromogranin A (CgA) positivity, and tumor progression." (PMID 39201255, 2024). "Preclinical data from lung adeno- and squamous cell carcinoma furthermore indicate that BCL-2 inhibitors such as APG-2575 were capable of reprogramming macrophages to a tumor suppressing M1 phenotype, thereby promoting the response to anti-PD-1 therapy." (PMID 38789691, 2024). "Docetaxel can induce apoptosis through BCL-2 phosphorylation, promoting tumor regression, and is largely employed in combination with many other chemotherapeutic agents to improve therapeutic efficacy." (PMID 38891056, 2024). "AEMA-g-WSC polyplexes, in combination with psi-hBCL2 (a vector expressing short hairpin RNA against BCL2 mRNA), inhibited tumor cell proliferation and tumor growth in vitro and in vivo, respectively, by inducing apoptosis." (PMID 38920928, 2024). "The apoptosis of tumor cells is closely related to Bax and bcl-2, and Bax and bcl-2 are proapoptotic factors and antiapoptotic factors." (PMID 39508039, 2024). "PXN, a cytoskeletal protein, when overexpressed, facilitated tumor progression and acted as an oncogene by regulating Bcl-2." (PMID 38183097, 2024). "In CD44+/CD133 + MiaPaCa2 cells, a decrease in miR-34 presence was combined with a rise in Notch/Bcl-2 and a higher concentration of tumor stem/progenitor cells, tumor sphere-forming cells, and tumor initiating cells." (PMID 38725047, 2024). "Compared with the control group, the tumor tissue is necrotic, the blood vessels in the tumor are atrophied, the protein expressions of BAX and Cleaved-Caspase-3 in the tumor are increased, and the protein expressions of Bcl-2 and Bcl-xL are decreased." (PMID 38633608, 2024). "The BCL-2 protein is the direct target of Venetoclax (VTC) (ABT-199), a selective BCL-2 inhibitor that alters the mitochondrial apoptotic pathway and causes tumor cell death." (PMID 39906657, 2024). "Specifically, exosomes derived from tumor cells transfected with stable miRNA-129-5p exhibited selective apoptosis induction by decreasing Bcl-2 expression and increasing Bax expression." (PMID 38298209, 2024). "Glabridin induces tumor cell apoptosis by upregulating the pro-apoptotic gene Bax and downregulating the anti-apoptotic gene Bcl-2 while inhibiting glycolysis by reducing HK2 and LDHA expression." (PMID 39723390, 2024). "Bcl-2 plays a role in inhibiting apoptosis as its high expression increases tumor cell proliferation." (PMID 39845799, 2024). "YAP inhibition abolished the ability of Bcl-2 to increase tumor cell migration and proliferation on high stiffness condition of culture, to stimulate in vitro fibroblasts migration and to induce fibroblasts activation." (PMID 38755629, 2024). "To establish a connection between the altered Bcl-2 conformation, the activation of Bax, and the induction of apoptosis, we probed the tumor sections with antibodies that recognize activated Bax and cleaved (active) caspase-3." (PMID 38329389, 2024).
tumor (continued). "On the other hand, Bcl-2 overexpression is correlated with clinical and paraclinical parameters and tumour resistance against cytotoxic treatment." (PMID 38698968, 2024). "IHC staining of tumor tissues showed increased Ki67 and Bcl2 expression and decreased BAX expression in the overexpression group, while the opposite trends were observed in the knockdown group." (PMID 39030638, 2024). "In conclusion, higher GATA3 expression was significantly associated with a more indolent BCC histological type, higher BCL2 expression, and a higher stromal tumor-infiltrating lymphocyte count." (PMID 38668712, 2024). "In vivo studies performed in tumor-bearing nude mice, showed that siRNA-Ch-HAD NPs effectively targeted tumor cells, resulting in reduced Bcl2 protein levels and inhibited tumor growth, indicating their potential for bladder cancer therapy." (PMID 39065565, 2024). "IHC results also showed that Ki67, BCL2, N-cadherin, and vimentin were downregulated, and Caspase3 and E-cadherin were upregulated in p65/S536D-overexpressing tumor tissues." (PMID 39498383, 2024). "Immunohistochemical data of tumor tissue and previous WB results consistently showed that Bcl-2 and Ki-67 were down-regulated, while cleaved casepase-3 and Bax were up-regulated in a dose-dependent manner." (PMID 38977966, 2024). "The BCL-2 antiapoptotic family consists of key molecules that regulate tumor cell apoptosis, including BCL-2, BCL-xL, BCL-w, and MCL-1." (PMID 39060763, 2024). "In this study, letrozole treatment markedly reduced Bcl-2 expression, increasing cell death and exhibiting letrozole-mediated tumor growth inhibition via enhanced apoptosis." (PMID 38622436, 2024). "Our results prompted us to refine the classification of mutations impacting the BCL2 TMD and elucidate those potentially providing an advantage for tumor progression or therapy resistance." (PMID 38670940, 2024). "Substantial in vivo tumour growth suppression with low toxicity; downregulated nuclear factor-κB and BCL-2 expression; inhibited expression of P-glycoprotein, MrP-1, BCRP, and triggered apoptosis." (PMID 39720730, 2024). "The sensitivity of malignant tumor cells to apoptosis can be efficiently boosted by either lowering Bcl-2 protein levels or suppressing Bcl-2 function." (PMID 39840282, 2024). "Numerous studies have identified the specific interaction between G0S2 and Bcl-2 at the mitochondria, disrupting the formation of the Bcl-2/Bax anti-apoptotic heterodimer complex, thereby regulating its anti-apoptotic activity in human tumor cells." (PMID 39707168, 2024). "VEN, a selective inhibitor of BCL-2 that effectively induces the intrinsic apoptosis of tumor cells, has attracted considerable attention." (PMID 38909249, 2024). "Other studies revealed that miR‐15 and miR‐16‐1 acts as tumour suppressors to induce apoptosis by repressing Bcl‐2, an anti‐apoptotic protein over expressed in malignant non dividing B cells and many solid malignancies." (PMID 39434198, 2024).
tumor (continued). "Subsequently, the deficiency of miR-338-5p in hypoxic cancer cells moderated the decrease in IL-6 expression and reactivated the anti-apoptotic STAT3/Bcl2 signaling pathway, thus impeding tumor cell death and improving the drug resistance of tumor cells." (PMID 37588219, 2024). "We further analyze the tumor characteristics that result in the development of intrinsic or inherited resistance to BCL-2 inhibitors." (PMID 39906657, 2024). "MiR-204 is known as a tumor suppressor that targets multiple oncogenes, including MYCN, BCL2, NTRK2 and PHOX2B, which are associated with tumor progression and chemoresistance in NB." (PMID 39594898, 2024). "C-Myc, MMP9, CyclinD1, and BCL-2 were tumor-related genes that have been identified to be regulated by NFκB signaling." (PMID 38581570, 2024). "QPCR was carried out with RNA obtained from tumor tissues, and it was found that the expression of ER-related genes PS2, c-Myc and BCL-2 in tumor tissues was significantly inhibited in the experimental groups treated with ATRA combined with Tamoxifen." (PMID 38714534, 2024). "In ccRCC, overexpression of anti‐apoptotic proteins such as Bcl‐2 and Bcl‐xL inhibited apoptosis and promoted the survival of tumour cells." (PMID 39011666, 2024). "Studies have demonstrated that dexamethasone enhances the anti-tumor efficacy of the BCL-2 inhibitor venetoclax." (PMID 38643300, 2024). "An FDA approved BCL2 inhibitor, venetoclax, was proven to block tumor growth and induce tumor regression in mice bearing high BCL2 expressing SCLC." (PMID 39103941, 2024). "The obtained extracellular nanoparticles, containing OMVs, were found to inhibited the growth of CT26 tumor in mice, while the expression of Bax protein was increased and the expression of Bcl-2 protein decreased." (PMID 39065214, 2024). "The reduced BAX/Bcl‐2 ratio in SuHx cells also appears to be driven primarily by increased Bcl‐2 expression, a finding consistent with various tumor cells, where Bcl‐2 expression is enhanced, leading to apoptosis resistance." (PMID 39175041, 2024). "The results showed that the expression levels of cleaved PARP, Bax, and cleaved Caspase 9 increased in both tumor cells after lumbrokinase treatment, while the expression level of Bcl-2 decreased accordingly." (PMID 39062456, 2024). "This class is known as a tumor suppressor and works by targeting the BCL2,MCL1, CCND1, and WNT3A genes." (PMID 38530760, 2024). "Mechanistically, W. coagulans MZY531 postbiotics inhibit tumor growth through the modulation of the Bax/Bcl-2/caspase-3 and JAK2/STAT3 apoptosis pathways and PI3K/AKT/mTOR and TGF-β/SMAD4 cell autophagy pathways." (PMID 39459634, 2024). "Consistent with gene expression analysis and immunohistochemical staining, immunoblot analysis revealed that p-STAT3, p-P65, Bcl-2, Bcl-xL and cyclin D1 levels in tumor tissues from KI mice were dramatically increased." (PMID 38607004, 2024). "Consistent with our data, 9‐ING‐41, a small molecule inhibitor of GSK‐3β, has demonstrated anti‐tumor activity in patient‐derived xenograft mice (PDX) of various human cancers including PDAC by inhibiting the NF‐κB target genes such as BCL‐2." (PMID 39632551, 2024). "Significant expression differences of CCNB1 and BCL-2 were observed in 501 PCa tissue samples compared to 52 non-tumor tissue samples, with PCa tissues exhibiting significantly higher expression of CCNB1 and lower expression of BCL-2." (PMID 39318781, 2024). "For instance, in vitro studies have demonstrated that a Bruton’s tyrosine kinase inhibitor, zanubrutinib, synergistically enhances the anti-tumor effects of a BCL2 apoptosis regulator (BCL2) inhibitor, navitoclax." (PMID 38844964, 2024).
tumor (continued). "The overexpression of Bcl‐2 is known to extend tumor cell survival, inhibit apoptosis, and enhance tumor dissemination and invasiveness." (PMID 39688352, 2024). "The results revealed a significant reduction in BCL-2 and Ki67 levels, indicating suppressed tumor proliferation activity and the induction of apoptosis by isiBCL-2 in vivo." (PMID 38685028, 2024). "IHC results showed that Bax and Bcl-2 expressions in tumor tissue significantly increased and decreased, respectively." (PMID 39456433, 2024). "The inhibition of tumor growth by NSC311152 in vivo was mediated by the reduced protein expression of RET, c-Myc, Bcl-2 and cyclin D1 in tumor tissues evaluated using western blotting." (PMID 38791433, 2024). "We discovered that Bcl-2 regulates the Hippo pathway in different tumor types, promoting cell migration, adaptation to higher stiffness culture condition and fibroblast activation." (PMID 38755629, 2024). "Conversely, the downregulation of LHPP, HMOX1, and BCL2 disrupt tumor-suppressive functions, oxidative stress management, and apoptotic processes, respectively." (PMID 39468431, 2024). "The downregulation of CXCR4 mRNA and MHC class I in addition to induction of apoptosis (increased levels of caspases 3 and 9 along with decrease in Bcl-2 levels) in tumor tissue was observed." (PMID 39210613, 2024). "As expected, CD10 and BCL-2 positivity in tumor samples were present in most low-grade cases, as in those with predominance of histologic grade 1/2." (PMID 39682103, 2024). "The results showed that melittin-induced mitochondrial ROS bursts decreased ΔΨm, inhibited Bcl-2 expression, and increased Bax expression in both cells and tumor tissues." (PMID 39519238, 2024). "When treated with solanine at a dose of 5 mg/kg, a reduction in tumor size coupled with modulation of the mitochondrial‐mediated signaling pathway, including the ratio of Bax and Bcl‐2, was noted." (PMID 39479710, 2024). "In this study, we observed that PDL1, PD1, SOD2, PARP, SET, TGF-ß, NF-kB, and BCL2 were highly expressed in the control tumor tissue." (PMID 38258094, 2024). "It then translocates into the nucleus, binding to the promoter elements of relevant target genes and ultimately participating in the expression of pro-tumor and anti-apoptotic genes such as BCL2, TWIST, thereby exerting tumor-promoting effects." (PMID 38279997, 2024). "Consistent with the dual BCL2/MYC translocation association with poor patient outcomes, VAL cells showed heightened proliferation in human IL6-conditioned media and caused rapid tumor expansion and early death in the engrafted mice." (PMID 39272864, 2024). "During tumorigenesis, dysregulation of apoptosis mechanisms often results from the upregulation of the anti-apoptotic protein BCL-2, leading to the malignant proliferation of tumor cells." (PMID 38685028, 2024). "The analysis revealed that Bcl2 is overexpressed in primary tumor as compared to the normal patients." (PMID 38223131, 2024). "Via establishing the c‐SRC and Bcl2 signaling pathways, miR‐34a blocks tumor proliferation and invasion and thus induces senescence." (PMID 38173189, 2024). "As such, a new therapy regimen based on tumour aetiology involves inhibiting the BCL-2 anti-apoptotic protein from overcoming the resistance of tumour cells to apoptosis." (PMID 39816318, 2024). "Phytochemicals play a crucial role in regulating the process of tumor cell apoptosis, augmenting the Bax/Bcl-2 ratio results in heightened caspase-3 activity, ultimately triggering the initiation of cancer cell apoptosis." (PMID 39435289, 2024). "Downregulation of NCAPG promotes the expression of caspase-3 and Bax while inhibiting anti-apoptotic protein Bcl-2 expression, thereby promoting mitochondrial-related apoptosis in tumor cells." (PMID 39763653, 2024).